ACAT1 (acetyl-CoA acetyltransferase 1)
Diseases named in the same sentence as ACAT1 in open-access papers (continued):
Sharing a sentence is not in itself a finding about the gene and the disease.
cancer (77 papers, 2012 to 2026). A tumor composed of atypical neoplastic, often pleomorphic cells that invade other tissues. "In numerous cancers, the accumulation of LDs is frequently associated with altered expression of DGATs, ACAT1, and PLINs, indicating their pivotal role in cancer progression." (PMID 41041279, 2025). "ACAT1 and CE-rich tumors were associated with higher aggressive potential and poor survival in many cancers." (PMID 35399074, 2022). "In order to understand the mechanisms underlying the suppressive effects of ACAT-1 inhibition on cancer cell growth, we performed cell cycle analysis." (PMID 31978092, 2020). "Knocking out the gene encoding Acetyl-Coenzyme A acetyltransferase 1 (ACAT1), which is an enzyme involved in the esterification of cholesterol, was shown to improve the proliferation and effector function of cancer-reactive T cells." (PMID 32708397, 2020). "More recent studies have associated ACAT1 expression and cancer." (PMID 39247186, 2024). "Furthermore, to investigate the molecular mechanism(s) underlying ACAT-1 mediated cancer progression, we studied the effect of ACAT-1 inhibition on cell cycle, apoptosis and mitochondrial membrane potential." (PMID 31978092, 2020). "ACAT1 is also associated with anti-cancer resistance, cancer cell proliferation, and cancer growth." (PMID 32586350, 2020). "Additionally, ACAT1-mediated accumulation of CE in cancer is often associated with proliferation, metastasis and bad prognosis, suggesting that LDs formation is associated with cancer proliferation and progression." (PMID 36158205, 2022). "Tetrameric ACAT1 is commonly upregulated in cells stimulated by EGF, and, in diverse human cancer cells, inhibition of tetrameric ACAT1 attenuated tumor growth." (PMID 40166933, 2025). "The process by which ACAT1 converts cholesterol into CE occurs in many types of aggressive cancers and catalyses the reaction between long-chain fatty acyl-CoA (saturated or unsaturated fatty acids containing 13–21 carbons) and intracellular cholesterol." (PMID 40723223, 2025). "By focusing on how metabolism and redox status influence the interplay between cancer cells and immune cell infiltration, we provided direct evidence that high oxidative stress mediated by ACAT1 retarded TLS formation in the TME." (PMID 40166933, 2025). "ACAT1 is the major isoenzyme expressed in all examined tissues, including cancer cells, while ACAT2 is mainly localized in lipoprotein-secreting cells (enterocytes and hepatocytes)." (PMID 39940954, 2025). "In various human cancer cells, including those from lung, leukemia, head and neck, and prostate cancers, ACAT1 activity is higher compared to corresponding normal cell lines." (PMID 39857793, 2025). "In summary, our results revealed how cancer-cell metabolic reprogramming regulates the antitumor immune response and identified ACAT1 as an important metabolic regulator for TLS-related antitumor immunity." (PMID 40166933, 2025). "PPAR signaling pathway has been previously reported to be regulated by NAT10 through ac4C modification of genes such as ELOVL6, ACSL1, ACSL3, ACSL4, ACADSB, and ACAT1, thus modulating fatty acid metabolism in cancer cells." (PMID 40123006, 2025). "The regulatory function of ACAT1 has been studied in other cancer types, but its role in BLCA is still limited." (PMID 38169575, 2024). "Increased levels of ACAT1 have been observed in cancers of the prostate, endometrium, breast, and liver." (PMID 39247186, 2024). "Subsequent research revealed that ACAT1 facilitates a metabolic switch in cancer cells, alternating between glycolysis and oxidative phosphorylation by acetylating PDP1 and PDHA1." (PMID 38817856, 2024).
cancer (continued). "GSEA revealed that ACAT1 was functionally enriched in pathways in cancer, cell adhesion molecules cams, oxidative phosphorylation, and cell cycle." (PMID 38169575, 2024). "Our data support ACAT1 as a target for induced differentiation and a promising strategy for cancer treatment." (PMID 39494339, 2024). "Subsequently, quantitative PCR was performed to measure HMGCR and ACAT1 mRNA expression in the lung tissue of our cancer patients." (PMID 37024569, 2023). "Avasimibe, an ACAT-1 inhibitor, elevates the level of free cholesterol in pancreatic, colorectal, and liver cancer cells, inducing ER stress and resulting in cancer cell apoptosis." (PMID 37700339, 2023). "While the role of ACAT1/CE accumulation is being studied in various cancers, information regarding their contribution in EOC is scarce." (PMID 35399074, 2022). "Suppressing Adenosine and IDO, increasing the mitochondrial function and cytokine production using PCG1, as well as catalase expression to counteract TME hypoxic conditions by ACAT1 are examples of TME metabolic alterations contributing to cancer improvement." (PMID 36419058, 2022). "Abnormal accumulation of acyl-CoA cholesterol acyltransferase-1 (ACAT1) and ACAT1-mediated cholesterol esterified with fatty acids (CE) contribute to cancer progression in various cancers." (PMID 35399074, 2022). "Overexpression of ACAT1 followed by increased CE accumulation in lipid droplets has been reported in a variety of cancer types." (PMID 35399074, 2022). "In many cancer types, active ACAT1 inhibits pyruvate dehydrogenase activity and deflects pyruvate to lactate production." (PMID 34584218, 2021). "Results showed a higher sensitivity to the ACAT-1 inhibition of cancer cells compared to the normal counterpart." (PMID 34109128, 2021). "An additional layer of PDC regulatory complexity, independent of its phosphorylation and mediated by acetyl-CoA acetyltransferase (ACAT1), has been described in certain cancers." (PMID 33808495, 2021). "ACAT1 overexpression and cholesteryl esters enrichment play a dual role in promoting cancer progression." (PMID 34109128, 2021). "The genetic silencing of SOAT1/ACAT1 or the pharmacologic blocking of its activity suppresses tumor growth in several cancer xenograft models." (PMID 35198567, 2021). "Collectively, these studies imply that ACAT-1 inhibition regulates cellular proliferation or cancer aggression via different pathways." (PMID 31978092, 2020). "AH disrupted the transformation between tetrameric and monomeric of ACAT1 which is critical for cancer cell proliferation." (PMID 32005728, 2020). "Significantly higher expression of ACAT-1 protein in cancer cell lines compared to normal controls was confirmed using ELISA." (PMID 31978092, 2020). "ACAT-2 expression was observed in all ovarian cell lines however the difference in expression levels between cancer cells and normal control cells is relatively less when compared to ACAT-1." (PMID 31978092, 2020). "Western blot analysis show significant expression of ACAT-1 protein in cancer cell lines compared to normal control cells." (PMID 31978092, 2020). "Given the additional suppressive effects of ACAT1 inhibitor on malignant properties of cancer cells, ACAT1 blockage thus has dual beneficial effects in cancer therapy." (PMID 30283400, 2018). "In this report, we molecularly targeted OXCT1 and ACAT1, to prevent cancer cells from recycling ketone bodies into Acetyl-CoA, which normally enters the TCA cycle, driving mitochondrial ATP production." (PMID 29108233, 2017). "Inhibitors of ACAT-1 are expected to have great value as cancer-targeting therapeutics, as CE accumulation only occurs in cancer tissues or cell lines." (PMID 27132508, 2016). "Therefore, the SCD1-ACAT1 axis regulates effector functions of CD8+ T cells, and SCD1 inhibitors and ACAT1 inhibitors are attractive drugs for cancer immunotherapy." (PMID 40861448, 2025).
cancer (continued). "Moreover, ACAT1, a key enzyme in lipid metabolism, has previously been investigated in other cancer types as a druggable target." (PMID 40790033, 2025). "In addition to the proven ways of isoleucine metabolism, ketogenic metabolism, and FAO, ACAT1 catalysis is also related to cancer." (PMID 39494339, 2024). "Here, we summarized the role of ACAT1 in the contexts of different cancers." (PMID 38720812, 2024). "Our data suggest that ACAT1 acts as an inhibitor of cancer initiation." (PMID 39247186, 2024). "Further studies underscore the close relationship between ACAT1 and malignant tumors." (PMID 38817856, 2024). "We examined the ACAT1 gene expression in pan-cancer samples and compared it to the expression in adjacent healthy tissues in the cancer genome atlas (TCGA) dataset to investigate whether low ACAT1 gene expression in cancer is a common occurrence." (PMID 39247186, 2024). "Altered acetyl CoA acetyltransferase 1 (ACAT1) expression has been reported in diverse cancers." (PMID 36816175, 2023). "Interestingly, several studies in diverse cancers revealed the oncogenic function of ACAT1 recently, which occurs through several mechanisms." (PMID 36816175, 2023). "This may be because ACAT-1 inhibition impairs Wnt/β-catenin signaling, thereby overcoming cancer cell metastasis." (PMID 37089950, 2023). "Recently, elevated enzyme activity of ACAT1 in various human cancer cell lines has been reported." (PMID 35178152, 2022). "Abnormal accumulation of ACAT1/CE may lead to resistance to drugs such as tamoxifen, gemcitabine, imatinib and cisplatin as shown in various in vitro and in vivo cancer models." (PMID 35399074, 2022). "In addition to promoting cancer aggressiveness, ACAT1/CE are also known to play an important role in drug resistance, which is the primary cause of EOC recurrence." (PMID 35399074, 2022). "Indeed, inhibition of ACAT1 using pharmacologic (avasimibe) or genomic (ACAT1 shRNA) agents suppressed cancer cell proliferation, migration and invasion in vitro and in vivo as reported in colon, pancreas, prostate and EOC models." (PMID 35399074, 2022). "For example, studies have revealed that it can lead to oxaliplatin resistance via activation of the PI3K/Akt pathway in HT-29 cells and contribute to cancer cell progression via the upregulation of ACAT1; additionally, it can increase proliferation and migration of HCT-116 cells." (PMID 35715761, 2022). "In support of these reports, inhibition of CE/ACAT-1 either by avasimibe (data not shown) or by ACAT-1 specific shRNA, significantly reduced the migration, invasion and proliferation properties of the ACAT-1 inhibited cancer cell lines compared to their respective scrambled controls." (PMID 31978092, 2020). "Recent studies have focused to ACAT1 and its effects on cancer cell growth." (PMID 29793481, 2018). "Therefore, ACAT1 is an attractive therapeutic target for certain types of cancer where large accumulations of CE are observed." (PMID 30283400, 2018). "Depletion of ACAT1 by shRNA reduces cancer proliferation and impairs cancer invasion." (PMID 29295482, 2017). "We further demonstrate that ACAT-1 inhibition-induced ER stress led to apoptosis of cancer cells." (PMID 27132508, 2016). "ACAT-1 expression was shown positive in cancer tissues, but marginal in the normal counterparts." (PMID 27132508, 2016). "However, there is limited report demonstrated the potency of ACAT1 in either cancer research or chemotherapy resistance." (PMID 25639359, 2015). "Therefore, 6 of the genes (ENC1, ACAT1, MSTC1, MADCAM1, RPL23 and SNRPB2) were found to be associated with cancer, genetic disorder or reproductive system disease within the same network." (PMID 22280244, 2012).
cancer (continued). "Since the cytosolic ACAT2 enzyme is involved in cholesterol synthesis but the mitochondrial ACAT1 plays a more prominent role in cancer, it may be possible that cancer cells take advantage of ACAT2-mediated attenuated PDC activity rather than enhanced ACAT2 activity for cholesterol synthesis." (PMID 37958351, 2023). "Furthermore, ACAT1 inhibition was reported to suppress cancer cell proliferation." (PMID 36479100, 2022). "Consistent with Yue and colleagues, pharmacological inhibition of ACAT1 reduced both cholesteryl ester levels and cell proliferation, which further adds to the growing body of literature promoting the potential for ACAT1 as an anti-cancer therapeutic target (see reviews)." (PMID 35033184, 2022). "Five core genes (ACAT1, PACS2, VDAC1, MFN1, and ATAD3A) playing critical roles in cancer were identified in this study." (PMID 36902617, 2023). "The results of immunohistochemistry (IHC) in the Human Protein Atlas (HPA) database showed that compared with normal tissues, ENOPH1, ACAT1, ALDH4A1, FAS, and ASPG are downregulated in cancer tissue than in normal tissue." (PMID 35992263, 2022). "We have recently reported increased levels of ACAT1 and CE in EOC cell lines compared to the primary ovarian epithelial cells (from normal ovaries), confirming ACAT1 mediated CE accumulation is a cancer-specific event." (PMID 35399074, 2022). "The recognition of these sites by multiple TKs coupled with the fact that phosphorylation occurs in a variety of primary cancers and cancer cell lines suggests that this is a common means of coordinately regulating PDH and ACAT1 activities." (PMID 33808495, 2021). "Then, we explored the TTK, C16orf54, PPAT, CD3EAP, SLCO2A1, ACAT1, and GAS2L3 genes in the CBioPortal for cancer genomics." (PMID 33402113, 2021). "ACAT-1 inhibition was reported to lead to down-regulation of the caveolin-1/MAPK pathway, which contributed to reduced cancer aggressiveness." (PMID 31978092, 2020). "They found that, in mice, inhibition of acetyl-CoA acetyltransferase 1 (Acat1) in CD8+ T cells restores their antitumor effect and reduces cancer progression and metastasis." (PMID 33194642, 2020). "Increased activity of Acetyl-coenzyme acetyltransferase-1 (ACAT1), an enzyme that can catalyze cholesterol esterification as well as lipase activity has also been seen in cancer cells, suggesting that CE may allow cancer cells to store and quickly access energy when needed." (PMID 33604295, 2020). "SIRT3 regulates pyruvate dehydrogenase that is acetylated by the acetyl-CoA acetyltransferase 1 (ACAT1); acetylation/deacetylation status of the dehydrogenase is important for the regulation of glycolysis in cancer cells." (PMID 27882448, 2017). "Based on these and other ketone-related studies, it appears that the enzymes driving ketone re-utilization, namely ACAT1 and OXCT1, would be excellent therapeutic targets for drug development, especially for the eradication of cancer stem cells (CSCs)." (PMID 29108233, 2017). "So, effective ACAT1 and OXCT1 inhibitors would be expected to phenotypically drive ATP depletion in cancer cells." (PMID 29108233, 2017). "It is worth noting that ACAT1 pS60 could be upregulated by MEK1/2 pathway, which often exhibits high expression level in cancer." (PMID 40289129, 2025). "ACAT1 tetramers, but not monomers, are phosphorylated and stabilized by enhanced Y407 phosphorylation observed in multiple human cancer cells." (PMID 38720812, 2024). "Avasimibe, also named as avasimin, has been developed as a potent non-specific ACAT1 inhibitor to impair cholesterol esterification in multiple cancer models." (PMID 38720812, 2024).
cancer (continued). "ACAT1 predominantly signals through inhibition of PDC by PDP1 and PDHA acetylation to enhance glycolysis and tumor growth, indicating the ACAT1-PDP1-PDHA axis a promising anti-cancer target." (PMID 38720812, 2024). "Nonetheless, our data points to the fact that ACAT-1 expression is greater in MDA-MB-231 cells chronically exposed to CDDP (MDACR), which might reflect events that occur in response to anti-cancer treatments." (PMID 36481936, 2022). "Notably, ACAT1 protein, whose mitochondrial levels are downregulated by TUDCA, was recently described to acetylate PDC and inactivate its function in cancer cells." (PMID 32582686, 2020). "Finally, we demonstrated that a naturally available substance, chlorogenic acid (CHA), could inhibit phosphorylation of ACAT1 and so delay GBM progression, CHA is a promising candidate to treat GBM because it could induce the differentiation of cancer cells." (PMID 39494339, 2024). "This could be corroborated by our proteomics functional analysis, where we found, for instance, a higher abundance of HADH, PLOD3 and ACAT1 (lysine degradation) and PFKL, NTRK1, PDHB and PDHA1 (central carbon metabolism in cancer) in control piglets compared to UL." (PMID 38409238, 2024). "Given a trend of increased ACAT-1 expression, concomitantly with higher CE content after CDDP treatment, this enzyme plays an important role in triggering metabolic changes in BC cells, contributing to the increased proliferation rate of MDA-MB-231 and different responses to anti-cancer therapy." (PMID 36481936, 2022). "Out of the 49 pieces of cancer tissues, 13 were identified as ACAT-1-negative and 36 were positive." (PMID 27132508, 2016). "In addition, high expression of fatty acid esterase (ACAT-1) in PC cells promotes esterified storage of free cholesterol, while inhibition of ACAT-1 leads to accumulation of free cholesterol, which ultimately leads to severe endoplasmic reticulum stress and apoptosis of cancer cells." (PMID 40356913, 2025).